SMC4 (structural maintenance of chromosomes 4)
Description:
Central component of the condensin complex, a complex required for conversion of interphase chromatin into mitotic-like condense chromosomes. The condensin complex probably introduces positive supercoils into relaxed DNA in the presence of type I topoisomerases and converts nicked DNA into positive knotted forms in the presence of type II topoisomerases.
Synonyms: SMC-4; hCAP-C; CAPC; SMC4L1; CAP-C
Tractability: PROTAC: ubiquitination databases record sites on it; its protein half-life has been measured.
Gene: Protein-coding gene on chromosome 3 (160,399,274 to 160,434,965, forward strand). Ensembl gene ENSG00000113810.
Subcellular location: Nucleus; Cytoplasm; Chromosome
Subcellular location (Human Protein Atlas): Cytosol; Nuclear speckles
Pathways (Reactome):
Cell Cycle: Condensation of Prometaphase Chromosomes; Condensation of Prophase Chromosomes
Gene Ontology:
Molecular function: protein binding; ATP binding; ATP hydrolysis activity; chromatin binding; single-stranded DNA binding
Biological process: mitotic chromosome condensation; positive regulation of chromosome condensation; meiotic chromosome segregation; mitotic sister chromatid segregation; B cell differentiation; cell development; cerebral cortex development; chromosome organization; immunoglobulin heavy chain V-D-J recombination; positive regulation of chromosome segregation; positive regulation of chromosome separation
Cellular component: condensin complex; cytosol; nuclear speck; nucleoplasm; nucleus; chromosome; chromosome, centromeric region; condensed nuclear chromosome; cytoplasm
Genetic constraint (gnomAD): Loss-of-function variants: 67 observed, 105.96 expected, observed/expected ratio (o/e) 0.63, 90% interval 0.52 to 0.77. The upper end of that interval is the gene's LOEUF score, 0.77, which puts it in group 3 of 6, group 1 being the genes least tolerant of losing a copy. Missense variants: 1,172 observed, 1,258.2 expected, observed/expected ratio (o/e) 0.93, 90% interval 0.89 to 0.98. Synonymous variants: 448 observed, 411.45 expected, observed/expected ratio (o/e) 1.09, 90% interval 1.01 to 1.18.
Homologues: Orthologues: chimpanzee SMC4 (99% identical), macaque SMC4 (98% identical), pig SMC4 (95% identical), dog SMC4 (94% identical), mouse Smc4 (90% identical), rat Smc4 (89% identical), rabbit SMC4 (86% identical), guinea pig SMC4 (85% identical), tropical clawed frog smc4 (77% identical), zebrafish smc4 (68% identical), Drosophila melanogaster glu (39% identical), Caenorhabditis elegans smc-4 (33% identical), and 1 more. Paralogues in human: SMC1B (22% identical), SMC1A (21% identical), SMC3 (17% identical), SMC2 (17% identical), CCDC157 (7% identical), CKAP4 (7% identical), CCDC122 (4% identical).
Diseases named in the same sentence as SMC4 in open-access papers:
SMC4 is named in the same sentence as 64 diseases in open-access papers, as found by Europe PMC text mining. Sharing a sentence is not in itself a finding about the gene and the disease. The quoted sentences say what the papers report.
glioma (29 papers, 2017 to 2025). A benign or malignant brain and spinal cord tumor that arises from glial cells (astrocytes, oligodendrocytes, ependymal cells). "To elucidate the molecular mechanism underlying SMC4-mediated malignant transformation in glioma cells, we first performed bioinformatics analysis across three independent glioma datasets." (PMID 40933894, 2025). "In gliomas, SMC4 overexpression has been linked to tumor progression, though its upstream regulatory mechanisms and functional implications in metabolic reprogramming remain poorly understood." (PMID 40933894, 2025). "Aerobic glycolysis (the Warburg effect) is a hallmark of glioma energy metabolism, and our data link SMC4 to this process through regulation of LDHA." (PMID 40933894, 2025). "The aggressiveness-promoting role of SMC4 in gliomas is associated with the activation of Smad expression and TGFβ transactivity." (PMID 28287612, 2017). "Understanding the biological function of SMC4 in glioma progression will not only advance our knowledge of the mechanisms underlying glioma aggressiveness, but also establish SMC4 as a significant prognostic factor or a potential therapeutic target for treating gliomas." (PMID 28287612, 2017). "Smc4, a core subunit of condensing, has been reported to be associated with a variety of tumors, such as hepatocellular carcinoma, prostate cancer, and lung adenocarcinoma, and activated TGFβ/Smad signaling has been reported to promote the aggressive phenotype of glioma." (PMID 37051542, 2023). "Using integrated multi-omics analyses of glioma datasets, we assessed SMC4 expression and its correlation with clinical outcomes." (PMID 40933894, 2025). "Collectively, these findings deepen our understanding of glioma pathogenesis and highlight SMC4 as a multifunctional therapeutic target with translational potential for improved diagnosis and treatment." (PMID 40933894, 2025). "The SRRS and nomogram provide robust tools for prognosis and personalized therapy, supporting the NFIA/SMC4 axis and downstream effectors as potential therapeutic targets for glioma." (PMID 40933894, 2025). "SMC4 was significantly overexpressed in glioma tissues, with higher expression correlating with advanced tumor grades and poorer patient survival (AUC > 0.82)." (PMID 40933894, 2025). "Leveraging multi-dataset analyses (GSE4290, GSE29796, GSE50161), we observed significantly elevated SMC4 expression in glioma tissues compared to normal brain parenchyma (P < 0.0001)." (PMID 40933894, 2025). "To systematically validate the oncogenic role of SMC4 in glioma, we generated stable SMC4-overexpressing and SMC4-knockdown U-251MG/LN229 cell lines via lentiviral transduction." (PMID 40933894, 2025). "To further validate the oncogenic function of SMC4 in glioma, we explored its impact on the migratory and invasive capabilities of glioma cells." (PMID 40933894, 2025). "Here, we identify SMC4 as a multifunctional oncoprotein driving glioma progression through dual mechanisms: activation of TGF-β/Smad-mediated metastasis and LDHA-dependent metabolic reprogramming." (PMID 40933894, 2025). "Both prior studies and our current investigations confirm that SMC4 orchestrates critical biological pathways driving glioma tumorigenesis and progression." (PMID 40933894, 2025). "Bioinformatics analyses reveal a strong positive correlation between NFIA and SMC4 in glioma datasets, validated by co-expression in clinical specimens." (PMID 40933894, 2025). "Collectively, these findings demonstrate that SMC4 promotes glycolysis in glioma cells by upregulating LDHA, thereby providing metabolic energy support for malignant proliferation." (PMID 40933894, 2025). "Our study establishes SMC4 as a therapeutic target with dual roles in glioma progression and metastasis." (PMID 40933894, 2025). "This NFIA/SMC4 regulatory axis represents a potential therapeutic target for glioma and underscores the importance of transcriptional networks in gliomagenesis." (PMID 40933894, 2025).
glioma (continued). "In summary, this work uncovers the multifaceted role of SMC4 in glioma biology and provides a translational framework for improving diagnosis and treatment." (PMID 40933894, 2025). "Future studies will explore SMC4’s role in glioma stem cells and resistance to standard-of-care therapies like temozolomide." (PMID 40933894, 2025). "SMC4 drives glioma progression through dual mechanisms TGF-β/SMAD-mediated metastasis and LDHA-dependent glycolysis regulated by NFIA." (PMID 40933894, 2025). "Taken together, our integrative multi-dataset approach establishes SMC4 overexpression as a molecular signature of glioma progression and a clinically relevant prognostic biomarker." (PMID 40933894, 2025). "Our analysis showed a positive correlation between SMC4 expression in gliomas and CD4 T cell activation." (PMID 39949776, 2025). "Western blot (WB) validation in primary human glioma specimens confirmed upregulated SMC4 protein levels." (PMID 40933894, 2025). "The IHC results corroborated the positive correlation between NFIA and SMC4 expression levels, showing a consistent trend in the human glioma specimens." (PMID 40933894, 2025). "Collectively, these in vitro and in vivo data demonstrate that SMC4 promotes glioma cell proliferation and drives cell cycle progression, establishing its critical role in glioma tumorigenesis." (PMID 40933894, 2025). "Our multi-omics analysis across multiple datasets (TCGA, CGGA, GEO, ProteinAtlas) revealed consistent upregulation of SMC4 in glioma tissues, with expression levels correlating with tumor grade and patient prognosis." (PMID 40933894, 2025). "SMC4 increases the migration, proliferation, and invasion of glioma cells in GBMs via acting downstream of MiR-433-3p." (PMID 37114037, 2023). "The immunohistochemistry results from The Human Protein Atlas database also showed that SMC4 protein level was clearly enhanced in glioma." (PMID 37007153, 2023). "Depth studies have shown that SMC4 overexpression through the activation of TGF β/Smad signaling promotes the invasive phenotype of glioma cells." (PMID 37007153, 2023). "The correlation between SMC4 expression and the prognosis of patients with glioma was calculated using the Kaplan Meier method." (PMID 37007153, 2023). "Overexpression of SMC4 can significantly improve the proliferation rate, migration rate, and invasion ability of glioma cells in vivo and in vitro, while the down-regulation of SMC4 is just the opposite." (PMID 37007153, 2023). "Bioinformatics analysis based on TCGA and CPTAC databases indicated that the expression of SMC4 mRNA and protein was significantly higher in glioma than in normal tissues (p < 0.001)." (PMID 37007153, 2023). "This study provides a new insight into the cofunction of SMC4 and the mechanism by which the TGF β/Smad pathway is hyperactivated in gliomas, indicating that SMC4 is a valuable prognostic factor and a potential therapeutic target in gliomas." (PMID 37007153, 2023). "Our study allowed us to identify the four-gene signature (CFH, GALNT3, SMC4, and VAV3) associated with the overall survival of glioma TCGA-LGG patients." (PMID 36539408, 2022). "Bioluminescent imaging further showed that SMC4 knockdown attenuated the tumorigenicity and progression of glioma cells." (PMID 35615996, 2022). "Glioma samples were classified into high‐SMC4 expression and low‐SMC4 expression groups based on median expression value of SMC4, and then, ssGSEA analysis was performed." (PMID 35615996, 2022). "Cell viability assays showed that SMC4 silencing apparently improve TMZ's capability to kill glioma cells in both U87 and U373 cell lines." (PMID 35615996, 2022). "Lastly, we proved that SMC4, which has the highest positive regression coefficient in our risk model, is strongly linked with malignant progression and TMZ resistance of gliomas in a E2F1‐dependent manner." (PMID 35615996, 2022).
glioma (continued). "The overexpression of SMC4 promotes glioma cell invasion by activating TGF-β/Smad signaling and is associated with poorer OS in patients with glioma." (PMID 35372377, 2022). "Three major immune conditions were observed in glioma patients and the expression of SMC4 was significantly suppressed in the immunologically quiet patients." (PMID 34868977, 2021). "In glioma and colorectal cancer, upregulated expression of SMC4 promoted the tumor cell growth rate, migration and invasion." (PMID 34403221, 2021). "has unveiled SMC4 functions to promote glioma proliferation via TGF-β pathways, the role of DNA damage repair-related function of SMC4 is not discussed." (PMID 34868977, 2021). "We plotted the landscape of DNA damage repair (DDR)-related genes and identified SMC4 as an independent prognostic marker with integrated bioinformatics analysis, which is overexpressed in different histologic subtypes of glioma." (PMID 34868977, 2021). "There have been several studies finding that the expression of SMC4 was higher in breast cancer, hepatocellular carcinoma, glioma and colorectal carcinoma than in normal tissues." (PMID 33460400, 2020). "SMC4 had been found highly expressed in several cancers, such as glioma, colorectal carcinoma, and hepatocellular carcinoma." (PMID 31871499, 2019). "Recently, SMC4 upregulation markedly promoted the glioma cell proliferation rate and migration and invasive capability in vitro and in vivo." (PMID 29467813, 2018). "The ability of SMC4 to promote glioma progression was further examined using an in vivo murine model." (PMID 28287612, 2017). "More importantly, Kaplan–Meier survival analysis demonstrated shorter survival in the mice bearing SMC4-overexpressing glioma than in the control group." (PMID 28287612, 2017). "The results suggest that SMC4 promotes glioma cell tumorigenicity in vivo along with increased proliferative and invasive capability." (PMID 28287612, 2017). "Herein, we found that SMC4 expression at both mRNA and protein level was markedly increased in glioma cells and clinical tissues and that it correlated with poor prognosis." (PMID 28287612, 2017). "Consistent with the published database, Oncomine and TCGA, the expression of not only SMC4 mRNA but also SMC4 protein was significantly higher in the glioma cell lines than in NHA." (PMID 28287612, 2017). "To further investigate the roles of SMC4 in glioma progression, we predicted its probable functions via bioinformatics analysis using the Gene Set Enrichment Analysis (GSEA) database." (PMID 28287612, 2017). "In the clinical specimens, both SMC4 mRNA and protein were significantly elevated in the seven glioma tissue samples as compared with the two normal brain tissue samples (left)." (PMID 28287612, 2017). "To identify the major pathways contributing to the SMC4-mediated aggressiveness of glioma cells, we carried out correlation analysis between SMC4 expression and the possible signaling pathways in the GSEA database." (PMID 28287612, 2017). "Collectively, these data reveal that SMC4 contributes to glioma cell proliferation and viability in vitro by accelerating G1–S transition." (PMID 28287612, 2017). "The key finding of the present report is that SMC4 contributes to the promotion of glioma cell proliferation, migration/invasion and tumorigenicity, and activates the TGFβ/Smad signaling pathway." (PMID 28287612, 2017). "The results indicate that SMC4 mRNA expression is elevated in glioma tissues in tandem with increased WHO tumor grade." (PMID 28287612, 2017). "To further validate that SMC4-mediated glioma cell aggressiveness takes place through TGFβ activation, we blocked the TGFβ pathway in SMC4-overexpressing cells by transfecting the cells with Smad4 siRNA or the TGFβ inhibitor LY2157299 monohydrate." (PMID 28287612, 2017).
glioma (continued). "In interphase cells, the majority of the SMC4 condensing complex was found in the cytoplasm, therefore positive SMC4 staining was predominantly localized in the cytoplasm of glioma cells (left)." (PMID 28287612, 2017). "Meanwhile, we found that the phosphorylated levels of TGFBR1, Smad2 and Smad3 and the nuclear levels of Smad2/Smad3 were markedly increased in the SMC4-overexpressing glioma cells but decreased in the SMC4-silenced cells." (PMID 28287612, 2017). "To explore the clinical significance of SMC4 expression in human gliomas, we first analyzed SMC4 mRNA expression in 123 glioma specimens (19 anaplastic astrocytoma and 81 GBM) and 23 normal brain tissue samples from the Oncomine database (GSE4290 specimens)." (PMID 28287612, 2017). "Through correlation analysis between SMC4 gene expression levels and TGFβ-related gene signatures, we predicted that SMC4 promotes glioma cell aggressiveness and activates the TGFβ/Smad pathway." (PMID 28287612, 2017). "Taken together, SMC4 protein upregulation in glioma contributes to glioma progression and correlates with poor prognosis of the disease." (PMID 28287612, 2017). "To investigate the biological role of SMC4 in glioma cell aggressiveness, we evaluated the effect of SMC4 on the tumorigenic activity of glioma cells." (PMID 28287612, 2017). "SMC4 overexpression markedly promoted the glioma cell proliferation rate and migration and invasive capability in vitro and in vivo, whereas SMC4 downregulation reduced it." (PMID 28287612, 2017). "In this study, we demonstrate that, patients with glioma had high SMC4 expression, which confers poor prognosis." (PMID 28287612, 2017). "Quantitative IHC analysis revealed that the mean optical density of SMC4 staining in glioma cells increased significantly with the WHO grade (right), suggesting that high SMC4 protein expression contributes to glioma progression." (PMID 28287612, 2017). "SMC4 overexpression markedly promoted the glioma cell proliferation rate and migration and invasive capability in vitro and in vivo, and SMC4 downregulation reduced it." (PMID 28287612, 2017). "To further understand the functions of SMC4 in glioma, we assessed the effect of SMC4 on glioma cell migration and invasion." (PMID 28287612, 2017). "We believe that SMC4 promotes glioma cell tumorigenicity in vivo along with the increased proliferative and invasive capability, and functions as a novel oncogene in glioma aggressiveness." (PMID 28287612, 2017). "In summary, we demonstrate that SMC4 upregulation promotes glioma cell aggressiveness, such as cell proliferation, migration/invasion and tumorigenicity." (PMID 28287612, 2017). "Structural maintenance of chromosomes 4 (SMC4), a core component of the condensin complex, is dysregulated in multiple cancers, but its role in glioma metabolism and metastasis remains unclear." (PMID 40933894, 2025). "Collectively, these in vitro and in vivo findings establish SMC4 as a critical facilitator of glioma metastasis by potently activating the TGF-β/SMAD signaling axis, highlighting its therapeutic potential as a target for inhibiting metastatic progression in glioma." (PMID 40933894, 2025). "ROC showed that the expression of SMC4 mRNA in glioma was 0.881 (95% CI: 0.866–0.896)." (PMID 37007153, 2023). "Currently, the regulation mechanism of SMC4 in gliomas is still unclear." (PMID 35615996, 2022). "Numerous studies have proved that SMC4 is involved in glioma molecular nosogenesis." (PMID 35992200, 2022). "In addition to bioinformatics analyses, we functionally confirmed the oncogenic role of SMC4 in gliomas in vivo and in vitro." (PMID 35615996, 2022). "Moreover, comparative analysis of the transcriptome program of the ICD-based DC vaccine with transcriptome data from the TCGA-LGG dataset identified a four-gene signature (CFH, GALNT3, SMC4, VAV3) associated with overall survival of glioma patients." (PMID 36539408, 2022).